CD4 (CD4 molecule)
Diseases named in the same sentence as CD4 in open-access papers (continued):
Sharing a sentence is not in itself a finding about the gene and the disease.
infection (continued). "Finally, we found that the vast majority of Spike-specific CD4+ T cell memory response induced by natural infection or mRNA vaccination is conserved also against Omicron variant." (PMID 35154116, 2022). "However, lungs from M. tuberculosis-infected Vhl cKO mice showed a reduced frequency of CD4 T cells at 4, 6 and 8 weeks after infection when compared to WT mice." (PMID 36064840, 2022). "CD4 T cell subsets preferentially killed by HIV are phenotypically distinct from those resistant to HIV-associated cell death, in a manner not fully accounted for by their susceptibility to productive infection." (PMID 35784348, 2022). "However, at the site of infection a significant increase in the levels of intracellular IFN-γ was detected in CD4+ T cells of capmatinib-treated mice compared to control mice." (PMID 35041723, 2022). "Durable CD8+ and CD4+ T cell responses have also been reported following infection and vaccination." (PMID 35102312, 2022). "However, no significant changes regarding the percentage of Bax+ caspase 3− CD4 T cells were observed in blood, spleen and mLN during the course of early infection." (PMID 36000842, 2022). "A multivariate analysis of a smaller cohort of MM patients treated with the Rd regimen found lower Hb (<100 g/L) to be an independent factor associated with the occurrence of infections, together with the number of circulating CD3+CD4+CD161+ cells prior to Len-dex treatment." (PMID 36233774, 2022). "Indeed, Th1 supporting cytokines and Th1 CD4 T cell responses to infection only reach levels of adult maturity around age 5–1050." (PMID 35851033, 2022). "Previous analysis of infected, purified myeloid cells also highlighted lower expression of CD4 in Holstein relative to Sahiwal cells, and together with alteration of surface marker expression following infection of the BL20 line, indicates the latter possibility as most likely." (PMID 35061738, 2022). "Also after IL-15 stimulation, naive CD4+ T cells were the most resistant to HIV infection, with an average infection of 1.2%, while TEM cells were the most susceptible, with an average infection of 16.8%." (PMID 35499323, 2022). "YFP+ CXCR3+ CD4+ T cells could be early immune responders that are able to migrate to areas of infection where they can rapidly induce a TH1 response." (PMID 35092032, 2022). "Like CD4+ cells, the CD8+ cell count is negatively associated with the severity of infection." (PMID 35837843, 2022). "Notably, specific CD4+/CD8+ cells produced after vaccination or natural infection act as memory cells, which can effectively protect against newly characterized SARS-CoV-2 variants." (PMID 35935974, 2022). "Co-staining of different immune cell subtypes in human PBMCs showed that the reduced infection of total PBMCs by avian-type HK-R2 was caused by reduced infection of natural killer (CD56+) cells and almost complete resistance of lymphocytes (CD4+ T cells, CD8+, T cells, CD20+ B cells)." (PMID 35359920, 2022). "The reduced CD4 T‐cell Th1 responses to SARS‐CoV‐2 peptide‐challenge in individuals recovered from mild COVID‐19 under the age of 40 raises questions regarding the long‐term protective immunity that natural infection imbues in the young." (PMID 35396852, 2022). "Gut CD4+ T cells transiently decreased in 3 animals but recovered to pre-infection levels." (PMID 35714165, 2022). "In fact, adoptive transfer of B and CD4+ T cells into Rag1−/− recipients dampened the protective effects of only transferring CD4+ T cells against wt B. melitensis 16M infection, further suggesting that infection of B cells leads to suppression of host inflammatory responses." (PMID 36620020, 2022). "Thus, the confocal microscopy indicates that SDR prior to infection of old mice results in the presence of CD4 T cells in the lung at 60 days expressing markers of IL-10 secreting regulatory cells." (PMID 36189368, 2022).
infection (continued). "Since we found more live bacteria in CD11bposCD11cpos moDC from mice infected with 4334 than H37Rv as early as day 8 post infection, we hypothesized that this could result in earlier antigen-specific CD4 T cell priming in the lung-draining lymph node." (PMID 35695454, 2022). "Approximately half of the amplified full-length single envelope-encoding clones had no significant activity for infection of cells expressing high levels of CD4 and CCR5 or CXCR4." (PMID 35727047, 2022). "Unfortunately, given the very low levels of CD101+ CD4 T cells after infection, we are unable to sort these cells and directly assess whether they harbor more virus at this time." (PMID 35867722, 2022). "However, 5 days after infection, an inflammatory response associated with overexpression of IFN-γ and TNF-α in serum, and PD-1 expression on CD4+ T cells are significantly increased." (PMID 36093199, 2022). "CD4 cells are crucial components of the immune system because they help the body fight infections." (PMID 36536709, 2022). "With regard to the T-cell responses, we and others have described that Spike-specific T-cell responses (CD4+ or CD8+ T-lymphocytes) after infection or prime/boost vaccination are more stable as compared to the respective humoral responses in healthy individuals." (PMID 36275672, 2022). "To further assess the potential of APs as PrEP candidates, we measured their inhibitory activity against trans-infection between cervical migratory cells and CD4+ T cells in a co-culture model of migratory cells isolated from ecto-cervical explants and a CD4+ T cell line, PM-1 cells." (PMID 36478892, 2022). "This led to the hypothesis that infection of CD4+CTLA-4 + T-cells elicited Nef-mediated concomitant downregulation of CTLA-4, which is believed to produce optimal conditions for viral replication, thereby promoting productive infection and HIV persistence." (PMID 35123267, 2022). "The cytotoxic potential of a CD4+ T cell population against B. abortus infection in mice has also been disclosed, but further studies are needed to unravel the exact contribution of this population during the chronic stage of infection." (PMID 35888979, 2022). "After observing the direct antibacterial effect of CD4-PP against uropathogens and its immunomodulatory effects, we investigated whether CD4-PP would facilitate the eradication of uropathogens during in vitro infection." (PMID 35821354, 2022). "Differences in the CD4+ T cell populations were negligible prior to challenge infection." (PMID 36140395, 2022). "In this regard, data from T. cruzi infection differs from those observed during infection with other intracellular parasites such as T. gondii and certain L. major strains, in which high frequencies of CD4+ T cells producing both IL-10 and IFN-γ were described." (PMID 35670567, 2022). "Importantly, infection of resting CD4 T cells and establishment of HIV latency can be enhanced through co-culture with antigen-presenting cells, infected or uninfected, or virus-producing endothelial cells." (PMID 35895672, 2022). "To characterize the immune response based on the infection route, we assessed how the frequency of circulating neutrophils, Ly6Chi monocytes, CD4+ and CD8+ T, immune cell populations crucial for parasite control, changed over the course of infection using flow cytometry." (PMID 35898505, 2022). "Similar observations were made at the level of DENV-specific CD4+ T cells, where the acute phase of infection was associated with a subset of CD4+ T cells that co-produced IL-10 and IFN-γ, but no altered phenotype was associated with DHFs." (PMID 35455361, 2022). "In the SILP, the percentage of CD8+ T cells, B cells and ILCs expressing IL-10 increased at day 7 (D7) post-infection with H. polygyrus compared to naïve controls, whereas the proportion of IL-10+ CD4+ T cells remained unchanged and there was a small decrease in IL-10+ myeloid cells." (PMID 35428872, 2022).
infection (continued). "Furthermore, DP CD4+CD8+ T cells can maintain a steady-state of the gut mucosa and inhibit pro-inflammatory cytokine release during pathogenic infection." (PMID 35761286, 2022). "Interestingly, CCR5 expression in Gag293-specific cells correlated inversely with the frequency of these specific cells (R = −0.59, P = 0.01), raising the possibility that low CCR5 expression protected HIV-specific CD4 + T cells from infection and depletion." (PMID 35082297, 2022). "The measurement of T-cell immune memory at 6 months post-infection showed that the positive ratios of memory CD4+ T cells and memory CD8+ T cells were 90% and 70%, respectively, and the proportion of memory CD4+ T cells was nearly double that of memory CD8+ T cells." (PMID 36189203, 2022). "ART administration also contributes to a partial control of the levels of inflammation and immune activation, but cannot restore them to pre-infection levels and similar to CD4+ T cell restoration, late ART initiation results in a more limited control of immune activation." (PMID 35062339, 2022). "Due to HIV-specific antibody production, HIV-infection is stabilized at this stage of the infection, meaning that the plasma viral RNA load, despite being high, remains stable, CD4+ T-cells counts increase slightly, and the immune system activation remains persistent." (PMID 35432307, 2022). "However, African green monkeys and pigs surviving NiV experimental infection showed increased CD4+ and CD8+ effector memory cells and/or increased activated T helper memory cells." (PMID 36611767, 2022). "Approximately 1000 genes were captured and showed significant changes in CD4 T cells from mesenteric LNs (mLNs) and pelvic LNs (pLNs) on day 10 following infection compared to uninfected controls, of which 493 genes showed significant differential expression in both mLNs and pLNs." (PMID 36000842, 2022). "Collectively, these data show that the majority of Spike-specific CD4+ T cell response is directed to non-mutated regions and, in any case, it is similar in Wuhan strain and Alpha variant infection." (PMID 35154116, 2022). "A central role in clearing PCV2 infection could be actually played by PCV2-specific, IFN-γ/TNF-α co-secreting CD4+ cells after vaccination and infection." (PMID 35215119, 2022). "The number of CD4+ ICOS+ T cells increases in lethal infection with disease progression." (PMID 35109868, 2022). "Tfh cells are CD4+ lymphocytes specialized in regulating the adaptive immune response in germinal centers by enabling the selection of specific high affinity B cells and modulating affinity maturation in infection and vaccination." (PMID 36341425, 2022). "Many cats appear to be able to cope with CD4+ cytopenia and remain free of serious infections." (PMID 35578381, 2022). "Thus, the strategy of using the surface expression of CD44 and CD11a allows us to define the features of the polyclonal CD4 T cell responses to infection." (PMID 35215193, 2022). "Productive, sustained, infection with HIV requires infection of CD4+ T cells." (PMID 35012346, 2022). "This suggests that we need to improve the CD4+ T-cell response and further study the CD4+ T-cell subsets to clarify which subsets are highly correlated with the maintenance of antibodies after immunization or infection, and provide direction for the improvement and optimization of vaccines." (PMID 36032096, 2022). "Previous studies have shown that after the resolution of infection with wild-type L. major parasites, i.e., leishmanization, the skin of healed mice harbors CD4+ TRM cells, and the activity of these cells is important for optimal immunity against reinfection with Leishmania." (PMID 35419001, 2022). "The second person, however, had a pre-infection HIV-specific immunity with CD4+ T-cell responses for Gag and Pol, which was identified at a time point of pre-infection, suggested to have strengthened his adaptive immunity against a rapid progression in HIV infection." (PMID 35746741, 2022).
infection (continued). "Together, these results establish that RNP nucleofection and cultivation of resting CD4+ T cells according to our protocol enables the functional characterization of genetically depleted host cell factors for the infection of HIV-1 and other viruses (like MeV)." (PMID 34949807, 2022). "Interestingly, we also found a lower CD4/CD8 ratio in BKV-infected patients, which indicated a higher risk of infection." (PMID 35694540, 2022). "Also, we showed evidence that pre-existing CD4 and CD8 T cell responses to sH1N1 were associated with protection against pH1N1 infection." (PMID 35858844, 2022). "Of the 4 patients with CD4 counts < 200 cells/mm3, three were treated for secondary infection, with 2 confirmed organisms and 2 deaths, while in 13 patients with CD4 counts > 200 cells/mm3, 5 were treated for secondary infection, with 3 confirmed organisms and 5 deaths." (PMID 35148782, 2022). "Interestingly, we recently reported that CD127-expressing memory CD4 T cells are resistant to productive infection by HIV, consistent with our current study." (PMID 35784348, 2022). "Following infection with 1/148 parasites, we observed that the mice receiving CD4+ T cells, but not the remaining experimental groups, succumbed to disease, indicating that CD4+ T cells are sufficient to induce cerebral trypanosomiasis." (PMID 35787830, 2022). "A robust CD4 T cell response is key to elimination of Ct infection." (PMID 36248887, 2022). "Indeed, CD4+ T cells are rapidly depleted during acute infection which has deleterious consequences for proper adaptive immune responses due to their role in providing stimulatory cytokines." (PMID 35062339, 2022). "Whereas it promotes viral replication by favoring CD4+ T cell infection in untreated individuals, it could promote latency reactivation in patients under cART treatment." (PMID 35943163, 2022). "The expression of proliferation marker Ki67 in AIM+ CD4+ T cells was dramatically upregulated in the individuals within 1–6 months post vaccination compared to the expression in those within 7–12 months post vaccination or in the infection-only group." (PMID 36494338, 2022). "Thus, for an immune response to be effective at preventing infection, it needs to be able to target incoming HIV-infected cells early in infection before resting CD4 cell HIV reservoirs are established." (PMID 35746615, 2022). "Interestingly, sialic acid was also preferentially expressed on the memory CD4+ T cells that were preferentially targeted for infection by HIV." (PMID 35787792, 2022). "Correspondingly, homozygous Zbtb7bR367Q mutants exhibited significant reductions of thymic and peripheral CD4 T cells, and during infection fewer brain infiltrating proinflammatory leukocytes were observed, confirming the role of CD4 T cell help in promoting ECM pathogenesis." (PMID 35646724, 2022). "Within the vaccinated groups, there were several animals that experienced severe CD4+ T cell depletion at timepoints surrounding vaccination (8 and 14 weeks post-infection), but were still able to elicit robust KEX1-specific IgG titers in response to α-GC+KEX1." (PMID 36561749, 2022). "Thus, vaccination and infection did meet “prepared” immune systems with preexisting systemic CD4+ T-cell immunity." (PMID 36268016, 2022). "Importantly, Vpr also mediated STAT5-activation during HIV-1 cell-to-cell infection of resting memory CD4+ T cells as evidenced by an increase in the intracellular levels of phosphorylated STAT5 (P-STAT5) under conditions where cells were not exposed to IL-7." (PMID 35417711, 2022). "Inbred strains of mice with well-characterized MHC class I and class II proteins enable epitope-specific tracking of T cell responses with synthetic peptides and derivation of MHC-peptide multimers that allow detailed characterization of the vaccine- or infection-elicited CD4 and CD8 T cells." (PMID 35215193, 2022).
infection (continued). "The study revealed that in VS-mediated, cell-to-cell infection, viral fusion did not occur until cell-associated viral particles were transferred into a trypsin-resistant endocytic compartment of the recipient CD4+ cell." (PMID 35323042, 2022). "Indeed, zinc supplementation reduces infection incidence and increases CD4 and CD8 numbers in older individuals." (PMID 36077216, 2022). "However, since the presence of “ready-to-act” CD4+CD44+Ly6C+ T-effector cells requires a persistent infection of Leishmania parasites, achieving durable protection through safer vaccination methods makes TRM populations more desirable to target." (PMID 35419001, 2022). "In addition, patients with postoperative infection complication had a lower preoperative CD4+ /CD8+ lymphocyte ratio." (PMID 36169250, 2022). "In an attempt to compensate for this, CD8+ T cells may increase their levels along with B cells secreting the polyclonal antibody anti-HIV (IgG) to clear or diminish the infection among CD4+ T cells." (PMID 36291681, 2022). "Combined with the observation that de novo infection of primary CD4+ T cells is also poorly efficient in vitro even through cell-to-cell contacts, this further strengthens the notion that host factors could exert an intrinsic block to HTLV-1 infection." (PMID 35893677, 2022). "In our previous studies, we have shown slow decline of viraemia over the first 5 years of life among ART-naive PNPs who maintain normal-for-age CD4+ T-cell counts, and also, we have shown that viremic control in PECs is only achieved after a median of 6.5 years of infection." (PMID 34581306, 2022). "CD4+ is an important immune cell that is primarily involved in infection control in the body." (PMID 35664433, 2022). "We next evaluated the decline of CD4 T cells in blood and tissues during acute SIVmac251 infection." (PMID 36000842, 2022). "Infection with CRF02_AG was positively associated with the ARTRM S162A that, in turn, was frequently observed with the administration of nevirapine, also associated with lower CD4 counts." (PMID 36229577, 2022). "Our results demonstrated reductions in CD4+ T cell expansion in response to infection, which we hypothesize contributes to CD8+ T cell dysfunction." (PMID 35505970, 2022). "This specific regulation of CCR5 expression on different cell types may protect from SIV infection (and subsequent death) the CD4+ T cell subsets critical to a mild course of infection, while the virus replicates in less dispensable cells." (PMID 35154162, 2022). "Here we show there is an age-related defect in the ability of the adaptative cellular immune response to control viral dissemination, with total PBMCs, CD8+ T cells and CD4+ T cells from younger donors being significantly better at control of viral spread measured by early phase infection." (PMID 36591233, 2022). "While we did not see significant adverse events in our well‐controlled animal population, infection risks and adverse effects of sustained CD4/CD40L depletion will need to be accounted for and compared to traditional regimens in any future application in humans." (PMID 36101963, 2022). "The infection levels of B cells, CD4+ T cells, and neutrophils have prognostic values for LUAD." (PMID 35795208, 2022). "SARS-CoV-2-specific CD4+ T-cell responses can be detected as early as 2-4 days after infection and can produce specific responses to almost all viral proteins, especially the Spike, M, and N proteins, during the recovery period, which are correlated with protein expression levels." (PMID 36189203, 2022). "There is some encouraging evidence that, due to the broad CD4+ and CD8+ T-cell responses against multiple SARS-CoV-2 structural proteins, it is unlikely that variants will escape the majority of T-cell immunity conferred by prior infection or vaccination." (PMID 35812370, 2022).